MT3 (metallothionein 3)
Description:
Binds heavy metals. Contains three zinc and three copper atoms per polypeptide chain and only a negligible amount of cadmium. Inhibits survival and neurite formation of cortical neurons in vitro.
Synonyms: GIF; GIFB; GRIF; ZnMT3
Tractability: No criterion of Open Targets' tractability assessment is met for any kind of drug.
Gene: Protein-coding gene on chromosome 16 (56,589,074 to 56,591,088, forward strand). Ensembl gene ENSG00000087250.
Pathways (Reactome):
Cellular responses to stimuli: Metallothioneins bind metals
Gene Ontology:
Molecular function: cadmium ion binding; copper ion binding; protein binding; protein kinase activator activity; zinc ion binding; antioxidant activity; metal ion binding
Biological process: activation of protein kinase B activity; cellular detoxification; cellular response to hypoxia; cellular response to oxidative stress; cellular response to reactive oxygen species; negative regulation of axon extension; negative regulation of cell growth; negative regulation of oxidoreductase activity; positive regulation of DNA-templated transcription; positive regulation of ERK1 and ERK2 cascade; positive regulation of gene expression; positive regulation of protein phosphorylation; positive regulation of vascular endothelial growth factor receptor signaling pathway; protein stabilization; removal of superoxide radicals; response to hypoxia; cellular response to cadmium ion; cellular response to copper ion; cellular response to zinc ion; detoxification of copper ion; intracellular monoatomic cation homeostasis; intracellular zinc ion homeostasis; negative regulation of neuron apoptotic process; negative regulation of neuron projection development; zinc ion transport; and 4 more
Cellular component: cytoplasm; inclusion body; perinuclear region of cytoplasm; cytosol; nucleus; synaptic vesicle; astrocyte end-foot; astrocyte projection; axon; dendritic spine; extracellular region; microtubule; mitochondrial outer membrane; ribosome
Genetic constraint (gnomAD): Loss-of-function variants: 8 observed, 11.02 expected, observed/expected ratio (o/e) 0.73, 90% interval 0.43 to 1.31. The upper end of that interval is the gene's LOEUF score, 1.31, which puts it in group 5 of 6, group 1 being the genes least tolerant of losing a copy. Missense variants: 75 observed, 84.84 expected, observed/expected ratio (o/e) 0.88, 90% interval 0.73 to 1.07. Synonymous variants: 32 observed, 31 expected, observed/expected ratio (o/e) 1.03, 90% interval 0.78 to 1.39.
Homologues: Orthologues: chimpanzee MT2A (100% identical), macaque MT3 (97% identical), dog MT-III (93% identical), mouse Mt3 (87% identical), pig MT3 (85% identical), rat Mt3 (84% identical), guinea pig MT3 (82% identical), zebrafish mt2 (54% identical). Paralogues in human: MT1F (66% identical), MT1A (65% identical), MT1G (65% identical), MT1H (65% identical), MT1B (63% identical), MT2A (63% identical), MT1HL1 (62% identical), MT1X (62% identical), MT1M (60% identical), MT4 (54% identical), MT1E (40% identical).
Diseases named in the same sentence as MT3 in open-access papers:
MT3 is named in the same sentence as 111 diseases in open-access papers, as found by Europe PMC text mining. Sharing a sentence is not in itself a finding about the gene and the disease. The quoted sentences say what the papers report.
Alzheimer disease (17 papers, 2008 to 2026). A progressive, neurodegenerative disease characterized by loss of function and death of nerve cells in several areas of the brain leading to loss of cognitive function such as memory and language. "Further studies are required to identify the redox-coupled protein dynamics associated with the reduced form of apo-GIF/MT-3 and their relevance to the molecular basis of Alzheimer’s disease." (PMID 41236814, 2025). "MT3 is well implicated in several neurodegenerative processes, including cerebral ischemia, Parkinson’s disease, and Alzheimer’s disease." (PMID 38866016, 2024). "Although metallothionein-3 (MT3), a brain-enriched form of metallothioneins, has been linked to Alzheimer’s disease, little is known regarding the role of MT3 in glioma." (PMID 32029749, 2020). "Previously, GFAP and MT3 have been linked to trauma, ischemia, and neurodegenerative diseases, including encephalomyelitis, multiple sclerosis, Parkinson’s disease, Alexander disease, Alzheimer’s disease, and amyotrophic lateral sclerosis." (PMID 38866016, 2024). "MT-3 possesses a unique neuronal growth inhibitory activity, and the levels of this intra- and extracellularly occurring metalloprotein are markedly diminished in the brain of patients affected by a number of metal-linked neurodegenerative disorders, including Alzheimer’s disease (AD)." (PMID 28538697, 2017). "This study developed a CRISPR activator (CRISPRa) system using lipid nanoparticles to selectively upregulate Mt3 in astrocytes, aiming to enhance Aβ endocytosis in an Alzheimer's disease (AD) mouse model." (PMID 41387343, 2026). "The uniqueness of MT3 among MT family members has gained attention in brain research, especially for Alzheimer’s disease, and MT3 is often referred to as the brain-specific MT21,24,25." (PMID 39085359, 2024). "The possibility to enhance the expression of MT‐3 or protect it from degradation is an attractive therapeutic target, because low levels of MT‐3 were found in brains of Alzheimer's disease (AD) patients." (PMID 28948092, 2017). "Metallothionein-3 (MT-III) is specifically expressed in the brain; however, it is downregulated, and thus deficient in Alzheimer's disease." (PMID 23997854, 2013). "MT3 was first detected in the brain of patients with Alzheimer's disease, identified as a factor inhibiting neuronal growth in culture and called neural GIF (growth inhibitory factor)." (PMID 20885975, 2010). "However, since the discovery of a new role of MT3 as a growth inhibitory factor (GIF) in the brain, specifically in neurons of patients with Alzheimer’s disease, the structure and function of MT3 have started gaining a great attention." (PMID 32843100, 2020). "Indeed, MT3 shows abnormal expression in each lesion in patients with Alzheimer’s disease (AD) as confirmed by immunohistochemistry, Northern blotting, and reverse transcription polymerase chain reaction (RT-PCR)." (PMID 32843100, 2020). "Among the genes being down-regulated in the brains of Eya3 mutants, several are reported to be down-regulated also in Alzheimer's disease, e.g. ARPP19, BIRC4, MT3, SYT1 or TTR." (PMID 19102749, 2008). "The mammalian MT3 protein shows a characteristic insertion of six residues at the α-domain when compared to that of MT1 and MT2 and an extra residue in the β domain (Thr), which is responsible for neuron growth inhibitory activity in Alzheimer disease." (PMID 21541013, 2011).
breast carcinoma (16 papers, 2005 to 2024). "Recently, expression of MT3-encoding mRNA MT3 has been associated with a worse prognosis of breast cancer and neuroblastoma patients, and it has also been shown that MT3 expression tightly correlates with the poor outcomes of chemotherapy." (PMID 38594765, 2024). "It has also been reported that MT-3 isoform overexpression is associated with a poor prognosis for patients with breast cancer." (PMID 21599891, 2011). "Similarly, MT3 overexpression has been reported to be associated with poor prognosis in breast cancer." (PMID 30139373, 2018). "Likewise, MT3 increase is associated with breast cancer invasion due to regulating MMP-3." (PMID 34572798, 2021). "In conclusion, our study shows that the C-terminal domain of MT3 confers dome formation in the MCF-7 breast cancer cells, whereas both the N-and the C-terminal domain of the molecule can confer growth inhibition in MCF-7 cells." (PMID 28545470, 2017). "Further studies to define the expression of the GAGE proteins in breast cancer and the mechanism by which MT3 inhibits GAGE gene expression in MCF-7 cells are currently hindered by the lack of antibodies specific to the individual GAGE family members." (PMID 28545470, 2017). "The expression of MT3 in breast cancer has also been observed in other studies and in triple negative breast cancers, it has been suggested that its expression is associated with poor prognosis." (PMID 28545470, 2017). "Direct interdependence between the increased expression of MMP3 and overexpression of MT3 was further confirmed by transfecting human breast cancer MDA-MB-231 cells with siRNA to silence the expression of MT3." (PMID 25933064, 2015). "In summary, we have shown that overexpression of MT3 in breast cancer cells increases their invasiveness, most probably via upregulation of MMP3 activity." (PMID 25933064, 2015). "Using immunohistochemical methods, increased cytoplasmatic MT3 expression was identified in human urinary bladder and breast cancer." (PMID 25933064, 2015). "In contrast to the MT1/2 isoforms, the role of MT3 in cancer progression is poorly understood, including breast cancer." (PMID 25933064, 2015). "To link the observed increased invasiveness of the triple-negative MDA-MB-231/BO2 breast cancer cells overexpressing MT3 with the clinical situation, we analyzed MT3 expression in 51 cases of TNBC." (PMID 25933064, 2015). "Moreover, the expression of MT3 in breast cancer cell lines was lower than that in the normal human breast epithelial cell lines." (PMID 35619902, 2022). "However, low expression of MT3 has been found in patients with ductal breast cancer with lymph node metastasis." (PMID 34572798, 2021). "In addition, studies have suggested that MT3 overexpression can increase the invasiveness of breast cancer cell by modulating MMP-3 expression." (PMID 30139373, 2018). "Moreover, MT3 overexpression is correlated with a poor prognosis in breast cancer, plays a role in oxidative stress regulation and inhibits proliferation of breast cancer cell lines." (PMID 29805752, 2018). "A corresponding immunohistochemical analysis of MT3 expression in a small archival set of patient samples of human breast cancers showed that all breast cancers stained positive for the MT3 protein and that the level of expression was associated with cancers having a poor prognosis." (PMID 28545470, 2017). "Although the role of IFI6 in slowing the growth of MT3 expressing breast cancers is not known, the fact that it is overexpressed will provide a starting point to define the mechanism underlying MT3’s ability to inhibit the growth of MCF-7 cells." (PMID 28545470, 2017). "The present study was designed to further define the role of MT3 expression in human breast cancer." (PMID 28545470, 2017).
breast carcinoma (continued). "It was found that the increased nuclear MT3 immunoreactivity of breast cancer cells correlated with the more aggressive phenotype, as the expression of MT3 reached its highest values in the most locally advanced tumors (pT3-pT4), and was more pronounced in cases at advanced disease stages." (PMID 25933064, 2015). "Therefore, in the present study, the impact of MT3 overexpression on the proliferation, migration, in vitro invasiveness, and tumorigenesis of breast cancer MDA-MB-231/BO2 cells was studied." (PMID 25933064, 2015). "To further assess the possible relationship between MT3 overexpression and down-regulation of MMP3, we created a specific loss-of-function phenotype using siRNAs in order to inhibit the expression of MT3 in breast cancer MDA-MB-231 cells." (PMID 25933064, 2015). "So far, the overexpression of MT3 in breast cancer cells has not been linked to their invasive properties." (PMID 25933064, 2015). "Our data suggest that MT3 may regulate breast cancer cell invasiveness by modulating the expression of MMP3." (PMID 25933064, 2015). "Taken together, it seems possible that effect of MT3 overexpression on the growth rate of breast cancer cells is dependent on cell type; however, the exact molecular mechanisms underlying this effect are currently unknown." (PMID 25933064, 2015). "Therefore, the present study was undertaken to evaluate the role of MT3 in breast cancer cell proliferation, tumorigenesis, migration, and invasiveness." (PMID 25933064, 2015). "In breast cancer, MT3 was found in the cytoplasm of cancer cells, with no expression in normal breast epithelial cells, and intensive MT3 staining was associated with patient poor outcome." (PMID 25933064, 2015). "Therefore, to clarify the role of MT3 in breast cancer progression, we analyzed the effect of MT3-overexpression on proliferation, invasiveness, migration, and tumorigenesis of breast cancer MDA-MB-231/BO2 cells." (PMID 25933064, 2015). "In contrast, levels of MT3 protein were shown to be elevated in bladder and breast carcinomas." (PMID 16351731, 2005). "In addition, in breast cancer, MT-3 expression is considered to be a marker of poor prognosis." (PMID 25015776, 2015). "Therefore, to determine whether overexpression of MT3 affects the proliferation potential of breast cancer cells, BO2/MT3/LUC/PURO and control BO2/LUC/PURO cells were subjected to MTT assay." (PMID 25933064, 2015). "The differential effect of MT3 and MT1E on the expression of GAGE genes suggests unique roles of these genes in the development and progression of breast cancer." (PMID 28545470, 2017). "The differential effects of MT3 and metallothionein 1E on the expression of GAGE genes suggests unique roles of these genes in the development and progression of breast cancer." (PMID 28545470, 2017). "An expansion of this study to a much larger archival set of patient samples showed that few of the breast cancers did not express MT3, but that the absence of MT3 expression was a favorable marker for disease outcome." (PMID 28545470, 2017). "These cells were chosen, as they do not express MT3, unlike all the other analyzed breast cancer cell lines." (PMID 25933064, 2015). "In the case of breast cancer, overexpression of MT3 inhibits the growth of MCF-7 and Hs587T cells, but not T47D, MDA-MB-231, or ZR-75 cells." (PMID 25933064, 2015). "The mRNA of MT-1 series named as A, E, F, G, H, X and MT-3 isoforms but not MT-1B and MT-4 isoforms have been detected in breast cancer tissues." (PMID 21599891, 2011). "In addition, the laboratory has shown that the MCF-7 breast cancer cell line does not express MT3 and that stable transfection and expression of the MT3 gene inhibits the growth of the MCF-7 cells." (PMID 28545470, 2017).
breast carcinoma (continued). "In order to create a gain-of-function cellular model based on the stable overexpression of MT3, we screened the cultured noncancerous (hTERT-HME1) and breast cancer cell lines (MCF-7, SK-BR-3, BT-474, MDA-MB-231 and MDA-MB-231/BO2) for the expression of MT3 mRNA and protein." (PMID 25933064, 2015). "Ueno and colleagues could not detect MMP-16 (MT3-MMP) in breast cancer tissue using Northern blot analysis, whereas we detected its mRNA in normal and breast cancer tissue by RT-PCR." (PMID 19531263, 2009).
gastric cancer (7 papers, 2005 to 2019). A primary or metastatic malignant neoplasm involving the stomach. "Conversely, DNA methylation of the MT3 promoter has been associated with the down-regulation of the MT3 gene in gastric carcinoma and esophageal squamous cell carcinoma." (PMID 21818286, 2011). "No significant hypermethylation was observed, even if we consider exclusively the intron 1, reported to be the region abnormally hypermethylated associated with low MT3 expression in gastric carcinoma cells." (PMID 20885975, 2010). "Upregulation of MMP14 and MMP16 (MT3-MMP) is involved in EMT, and associated with the aggressiveness of human ovarian, breast and gastric cancer." (PMID 28399108, 2017). "On the contrary, in esophageal squamous cell cancer and adenocarcinoma of the esophagus—as well as in gastric cancer—MT-3 expression decreases, as compared with normal tissue." (PMID 25015776, 2015). "In contrast, in human esophageal cancers and gastric cancer, MT-3 expression has been seen to be frequently downregulated due to the increased DNA methylation in comparison with nonmalignant tissues of these organs." (PMID 25015776, 2015). "In gastric carcinomas MT3 expression was found to be markedly reduced, but there was no indication of any relationship to outcome in this report." (PMID 16351731, 2005). "Notably, DNA methylation of some MT isoforms in gastric cancer, like MT1A, MT1B, MT1H, MT1M, MT3, and MT4, was higher than their paired normal tissue except remaining isoforms." (PMID 31380415, 2019). "Our results are comparable to those obtained during the examination of esophageal and gastric cancers, where MT-3 expression had no impact on patients’ clinical or pathological data or on patient survival." (PMID 25015776, 2015).
prostate carcinoma (7 papers, 2010 to 2025). A carcinoma that arises from epithelial cells of the prostate gland. "Meanwhile, MT3 gene expression was upregulated in arsenic-transformed human urothelial cells and arsenic-treated prostate carcinoma cells." (PMID 30813460, 2019). "The results of upregulation of MT3 by arsenic are consistent with those of a previous study on prostate carcinoma LNCaP cells." (PMID 30813460, 2019). "Contrary to that, the current studies in the androgen-independent prostate cancer cells demonstrate that the endogenous up-regulation of MT-3 can inhibit cell growth." (PMID 29435113, 2018). "It was recently shown that MT3 increases proliferation and enhances tumorigenesis of prostate cancer cells." (PMID 25933064, 2015). "On the other hand, it was recently shown that MT3 overexpression in the same PC-3 prostate cancer cells enhances cell growth in vitro and tumorigenesis in vivo." (PMID 25933064, 2015). "A previous study in prostate cancer PC-3 cells revealed that overexpression of MT3 significantly increased cell proliferation, invasion and tumorigenic activities both in vitro and in vivo." (PMID 24962166, 2014). "Previous studies have illustrated NDRG1 as a downstream gene of MT3 in prostate carcinoma cells." (PMID 30813460, 2019). "However, enhanced cell invasiveness has been observed when prostate cancer PC-3 cells were forced to overexpress MT3." (PMID 25933064, 2015). "Indeed, MT3 has been considered for a long time as a non metal-inducible gene in normal astrocytes and neurons cultures, but recently Wei and co-workers showed MT3 induction after zinc treatment in prostate cancer cells." (PMID 20885975, 2010). "In one study cadmium and arsenic enhanced the expression of metallothioneins in prostate cancer cells, specifically MT1 MT2 & MT3 thus resulting in significant increase in cancer cell proliferation & invasion." (PMID 40860840, 2025). "It has been recently found that metallothionein-3 (MT3) enhances the invasiveness and tumorigenesis of prostate cancer cells." (PMID 25933064, 2015). "Although studies suggested that hypoxia upregulated MT3 in human prostate carcinoma PC-3 cells and adipocytes, no mechanisms were illustrated in their reports." (PMID 30813460, 2019).